RNU6-1183P (RNA, U6 small nuclear 1183, pseudogene)
Gene: Small nuclear RNA gene on chromosome 12 (101,871,742 to 101,871,801, reverse strand). Ensembl gene ENSG00000252863.
Homologues: Orthologues: guinea pig U6 (87% identical), rat LOC120094417 (87% identical), pig U6 (82% identical). Paralogues in human: RNU6-16P (97% identical), RNU6-38P (97% identical), RNU6-883P (97% identical), RNU6-1005P (95% identical), RNU6-1106P (95% identical), RNU6-1145P (95% identical), RNU6-1214P (95% identical), RNU6-1304P (95% identical), RNU6-247P (95% identical), RNU6-333P (95% identical), RNU6-393P (95% identical), RNU6-39P (95% identical), and 1286 more.